RN7SKP24 (RN7SK pseudogene 24)
Gene: Miscellaneous RNA gene on chromosome 9 (34,478,622 to 34,478,905, forward strand). Ensembl gene ENSG00000251697.
Homologues: Orthologues: chimpanzee 7SK (94% identical), mouse Gm55475 (44% identical). Paralogues in human: 7SK (55% identical), RN7SKP187 (55% identical), RN7SKP291 (55% identical), RN7SKP133 (54% identical), RN7SKP165 (54% identical), RN7SKP178 (54% identical), RN7SKP118 (53% identical), RN7SKP149 (53% identical), RN7SKP4 (53% identical), RN7SKP176 (53% identical), RN7SKP184 (53% identical), RN7SKP76 (53% identical), and 283 more.